ADRB3 (adrenoceptor beta 3)
Diseases named in the same sentence as ADRB3 in open-access papers (continued):
Sharing a sentence is not in itself a finding about the gene and the disease.
childhood asthma (1 paper, 2012). "Moreover, the IL4Ra and INSIG2 gene combination interacted with GSTP1, STAT6, ADRB2, ADRB3, IL13 and EPHX1 exon 3 to reveal a high training-balanced accuracy above 58.38% in childhood asthma." (PMID 22355322, 2012).
COVID-19 (1 paper, 2021). A disease caused by infection with severe acute respiratory syndrome coronavirus 2. "Salmeterol targets on seven non-n-COV host proteins (ADRB1, ADRB2, ADRB3, AOX1, DRD3, KCNH2, and THPO), meaning that it may not act on COVID-19 via directly targeting COV host proteins." (PMID 34539756, 2021).
hyperthyroidism (1 paper, 2022). Overactivity of the thyroid gland resulting in overproduction of thyroid hormone and increased metabolic rate. "Adrb3 mRNA levels in BAT were not affected by hyperthyroidism at any temperature." (PMID 36467699, 2022).
Immunodeficiency (1 paper, 2022). Failure of the immune system to protect the body adequately from infection, due to the absence or insufficiency of some component process or substance. "Thus, persistent delivery of costimulatory signals via ADRB3, as may occur during tumorigenesis or viral infections, can exhaust the naïve T-cell pool and is sufficient to induce lethal immunodeficiency." (PMID 35145073, 2022).
multiple myeloma (1 paper, 2023). "To investigate the expression levels of ADRB1, ADRB2, and ADRB3 in human multiple myeloma cell lines, we consulted the Lombardi and Heidelberg‐Montpellier cohorts." (PMID 36245401, 2023). "ADRB2 was expressed in plasma cells of healthy individuals and at all stages of multiple myeloma progression (MGUS, SMM, MM), while ADRB3 was expressed at low levels." (PMID 36245401, 2023).
sarcopenia (1 paper, 2024). Progressive decline in muscle mass due to aging which results in decreased functional capacity of muscles. "Thus, specific ADRB3 gene polymorphism and epigenetic changes may impact sarcopenic development; however, data on the genetic involvement of ADRB3 in sarcopenia or SO is scarce." (PMID 38397196, 2024).
viral infections (1 paper, 2022). "T-cell exhaustion is a state of T-cell dysfunction that arises during viral infections and cancer, and the ADRB3 signaling might play a role in this process." (PMID 35145073, 2022).
tumor (37 papers, 2004 to 2026). "In addition, tumor-derived IL-6 and adrenoceptor beta 3 (β3-AR) activation is associated with CAC mediated adipose tissue browning." (PMID 37205195, 2023). "Since β-blockers antagonise the β-adrenergic receptors (β-ARs) in the cardiovascular system, we first evaluated the expression pattern of β-AR genes ADRB1, ADRB2 and ADRB3 in MB tumours from a cohort of 240 patients." (PMID 35816899, 2022). "We previously demonstrated that ADRB3 promotes tumor cell proliferation and inflammation through activation monocyte-derived alveolar macrophages in non-small cell lung carcinoma." (PMID 35145073, 2022). "After 15d of M5D1 treatment, the lymphocytes and monocytes from tumor-bearing mice showed an average 1.7- or 1.4-fold increase in ADRB3 expression, respectively, compared with non-tumor-bearing mice." (PMID 32514619, 2020). "In NSCLC patients, we confirmed that upregulation of ADRB3 expression correlates with tumor progression and poor prognosis." (PMID 32514619, 2020). "By evaluating the relationship between ADRB3 expression and clinicopathologic parameters, we found that high expression of ADRB3 was strongly correlated with poor tumor differentiation and clinical stage." (PMID 32514619, 2020). "Our study demonstrated that tumor samples exhibited a higher expression pattern of ADRB3 by analyzing NSCLC tissue microarrays." (PMID 32514619, 2020). "During 2 weeks after subcutaneous inoculation of LLC cells, we observed almost equal tumor growth in both ADRB3−/− and ADRB3+/+ mice." (PMID 32514619, 2020). "Circulating monocytes are recruited to the lung, where they differentiate into monocyte-derived alveolar macrophages (Mo-AMs), so the immunofluorescence staining of bone marrow, blood and tumor tissue for ADRB3 was performed." (PMID 32514619, 2020). "Further we compared ADRB3 expression with various tumor entities showing its exclusive expression in ES." (PMID 27447745, 2016). "To determine whether deletion of ADRB3 affects PMN for the malignant tumor cells, we analyzed the expression of several genes related to inflammation, macrophages and T cells by IHC using the specimens of mice lung tissues." (PMID 35145073, 2022). "Moreover, ADRB3 expression was markedly high in activated disseminated tumor cells, myeloid-derived suppressor cells (MDSCs), lymphocytes and neutrophil extracellular traps of patients." (PMID 35145073, 2022). "Interestingly, the gene expression of ADRB3 was minimal detected in most types of tumor and adjacent-tumor tissues, including HCC." (PMID 34593796, 2021). "Genetic and pharmacologic inhibition of ADRB3 reverses tumor growth and inflammation in mouse." (PMID 32514619, 2020). "Based on ADRB3 expression in cancer cells, Mo-AMs, monocytes and lymphocytes, we wondered whether ADRB3 would modulate tumor immunity in vivo." (PMID 32514619, 2020). "ADRB3 was localized in the cytoplasm and nucleus of tumor cells." (PMID 32514619, 2020). "Therefore, we propose that the ADRB3 is a major tumor driver and a vulnerability in TNBC." (PMID 35145073, 2022). "To validate the role of ADGRA2 and ADRB3 expression in chemotherapy response and prognosis, we used a NACBC validation set, which consisted of 156 pre-treatment tumor samples of BC patients who received NAC with follow-up information available." (PMID 38217005, 2024). "Next, we analyzed the expression of main NE and EPI receptors, adrenergic receptors (ARs) in tumor sites, including α-adrenoceptor (α1-AR or ADRA1, α2-AR, or ADRA2) and β-adrenoceptors (β1-AR or ADRB1, β2-AR or ADRB2, β3-AR or ADRB3)." (PMID 34593796, 2021). "Compared to the expression levels in normal tissue, other genes, such as ADRB3, BTG2, DUSP4, RAD51 or FBLX7, were downregulated in specific tumor types, and ANG, ESD and STL7 were downregulated in most tumor types." (PMID 31159852, 2019).
tumor (continued). "The first relevant observation was that tumor growth in the prostate was slightly delayed when mice were lacking β2- or β3-AR singularly, but it was severely compromised in ADRB2−/−ADRB3−/− mice." (PMID 32486190, 2020). "We found that lymphocytes isolated from non-tumor-bearing mice expressed very low to undetectable ADRB3, whereas ADRB3 expression was higher in lymphocytes (4.8-fold) and monocytes (11.4-fold) from tumor-bearing mice compared with non-tumor-bearing mice." (PMID 32514619, 2020). "Furthermore, in a xenograft model using ADRB2 and ADRB3 double knockout mice (ADRB2−/−, ADRB3−/−), lowered human tumor cell dissemination to lymph nodes and distant organs was observed." (PMID 25629002, 2014). "Whether stromal ADRB2 and ADRB3 affect the metastatic process could not be addressed in this model system as tumor development was severely compromised in ADRB2−/−, ADRB3−/− mice." (PMID 25629002, 2014). "After verification that ADRB3 is not expressed on CD8+ T cells, we hypothesized that fratricide could occur due to cross-reactivity based on peptide resemblance of ADRB3295 and yet unidentified non-tumor associated antigens presented on the T cell surface." (PMID 27447745, 2016). "Our findings showed that the expression level of ADRB2 and TH in tumor tissues of sleep-deprived mice was significantly higher than those in the normal sleep group, while the expression levels of ADRA1, ADRA2, ADRB1, and ADRB3 showed no significant changes." (PMID 40276761, 2025).
cancer (35 papers, 2002 to 2026). A tumor composed of atypical neoplastic, often pleomorphic cells that invade other tissues. "ADRB3 has been proven to be a poor prognostic factor that accelerates cell proliferation in a variety of human cancers." (PMID 38217005, 2024). "The positive rate of ADRB3 expression in cancer tissue was 92.1% (210/228), of which 56.7% (119/210) were intermediate and strongly positive." (PMID 35145073, 2022). "We detected numerous ADRB3-rich NETs in peripheral blood from patients, suggesting that cancer cells can induce NETs formation and neutrophil recruitment via ADRB3." (PMID 35145073, 2022). "In this study, we report that both cancer cells and Mo-AMs robustly express beta 3-adrenergic receptor (ADRB3) in NSCLC." (PMID 32514619, 2020). "ADRB3 is likely to be a novel promising therapy target for cancer, so we've developed anti-ADRB3 monoclonal antibodies." (PMID 32514619, 2020). "More recently, the involvement of ADRB3 in metabolic reprogramming of melanoma, the promotion of immune-tolerance, and in regulation of cancer differentiation has been described." (PMID 32514619, 2020). "In the present study, using tissue microarrays and ADRB3 knockout MMTV-PyMT mice models, we report that ADRB3 expression correlates with BC aggressiveness, and leads to BC progression, metastasis, and immunosuppression by preventing either cancer cells or IMCs from exiting cell cycle." (PMID 35145073, 2022). "In addition, we highlight that ADRB3 expression is not only restricted to cancer cells, but it is also expressed in activated DTCs, proliferative MDSCs and activated T cells." (PMID 35145073, 2022). "The positive rate of ADRB3 in cancer tissues was also correlated with the TNM stage (S)." (PMID 35145073, 2022). "The expression rate of ADRB3 in cancer tissues was positively correlated with the malignant degree." (PMID 35145073, 2022). "The higher the malignant tumor grade, the stronger the expression of ADRB3." (PMID 35145073, 2022). "However, cancer cells chronically induce ADRB3 expression in IMCs as important ‘gatekeepers’ that prevent cell cycle exit linked terminal differentiation." (PMID 35145073, 2022). "In addition, the overexpression of ADRB3 has been found in several cancer types, including breast cancer, gallbladder cancer, colorectal cancer." (PMID 32514619, 2020). "In contrast, both cancer cells and AMs expressed ADRB3 at higher level in cancerous tissue." (PMID 32514619, 2020). "We successfully developed a novel ADRB3 monoclonal antibody called M5D1, which can targeted kill cancer cells and enhance antitumor immune responses by targeting immune cells." (PMID 32514619, 2020). "In conclusion, our findings shed light on the role of ADRB3 in NSCLC and cancer-related inflammation, thereby highlighting its potential as a therapeutic target." (PMID 32514619, 2020). "However, cancer cells may induce naïve T cell to arrest in G1 phase and subsequent senescence by awakening quiescence through upregulation of ADRB3 without antigen stimulation." (PMID 35145073, 2022).
metabolic disorders (29 papers, 2011 to 2025). "The Chinese researchers had shown that ADRB3 R64 allele was associated with increased BMI and weight and research group from Poland had found the protective effects of the ADRB3 Arg64 polymorphism against metabolic disorders." (PMID 21992420, 2011). "Although the mechanistic link between mutations/polymorphisms in ADRB3 and metabolic disease in humans remains to be established, it will be important to determine whether administration of a β3-AR agonist could be used to treat these conditions." (PMID 34100382, 2021). "The aim of this study was to determine the relationship between PPAR gamma-2 (Pro12Ala, C1431T) and ADRB3 (Trp64Arg) polymorphisms and serum adipocytokines (adiponectin, visfatin, and resistin) and metabolic disorders in 176 postmenopausal women with increased body mass (BMI ≥ 25 kg m−2)." (PMID 27246401, 2016). "This study reveals how signals from the suprachiasmatic nucleus coordinate the metabolic flexibility of BAT, through a adrenergic receptor ADRB3-S100B signaling axis, thereby identifying a new therapeutic target for metabolic disorders." (PMID 41343575, 2025).
ADRB3 also shares sentences with these, for which no sentence is quoted: melanoma (21 papers); cardiovascular diseases (13); overactive bladder syndrome (10); coronary heart disease (5); acute myocardial infarction (4); insulin dependent diabetes mellitus (4); Alzheimer disease (3); atherosclerosis (3); chronic kidney disease (3); endometrial cancer (3); fatty liver disease (3); heart disease (3); hypertrophy (3); myeloid leukemia (3); myocardial ischemia (3); neuroblastoma (3); nonalcoholic fatty liver disease (3); peripheral arterial disease (3); Polyuria (3); pulmonary hypertension (3); retinopathy (3); Sepsis (3); Urinary incontinence (3); benign prostatic hyperplasia (2); benign tumor (2); bronchopulmonary dysplasia (2); cardiomyopathies (2); chronic heart failure (2); Cirrhosis (2); colorectal cancer (2).
A further 85 diseases each share a sentence with ADRB3 in 2 papers or fewer.